GSTM3 (glutathione S-transferase mu 3)
Diseases named in the same sentence as GSTM3 in open-access papers (continued):
Sharing a sentence is not in itself a finding about the gene and the disease.
cancer (continued). "Finally, we found GSTM3/4 expression were significantly correlated with multiple anti-cancer drugs, especially in AICAR, AT7519, PHA-793887 and PI-103." (PMID 35965498, 2022). "An in-depth study of the regulatory mechanism related to the abnormal expression of GSTM3 and the effect of GSTM3 in various cancers may help prevent cancers and promote targeted treatment." (PMID 34490047, 2021). "Furthermore, WRS and SEM1, downregulated genes in GSTM3 downregulation, showed poor correlation with treatment outcomes in patients with cancer." (PMID 34209254, 2021). "Positive staining for GSTM3 was detected in the cytoplasm of cancer cells." (PMID 32984010, 2020). "We suggest that GSTs expression (GSTM3 or GSTP1) could be involved in modulating detoxification processes in cancer cells, and therefore, may participate in the survival response to conventional chemotherapy in patients." (PMID 29774096, 2018). "Unfortunately, despite the known function of GSTM3 rs3814309, there are no data describing its exact clinical impact, whether on treatment efficiency or on cancer risk." (PMID 39596349, 2024). "Thus, GSTM3 function appears to be context dependent and may vary with different cancer types." (PMID 33482859, 2021). "Glutathione S-transferase mu-3 (GSTM3) has been shown to exert different functions in the progression and development of various cancers, except for PC." (PMID 32984010, 2020). "In our study, we found these anti-cancer drugs could significantly enhance the level of GSTM3/4 by a negative feedback way, resulting in promoting drug metabolism, especially in AICAR, AT-7519, PHA-793887 and PI-103." (PMID 35965498, 2022).
tumor (26 papers, 2014 to 2026). "Studies have shown that GSTM3 has different polymorphisms in various tumor cells and participates in the regulation of tumorigenesis, cell invasion, metastasis, chemical resistance, and oxidative stress." (PMID 34490047, 2021). "We also explored the effects of GSTM3 alteration on tumor progression and metabolism of PC and the possible underlying mechanism." (PMID 32984010, 2020). "If a progestogenic drug like MPA can bind to and inhibit GSTM3's activity, it could impair the enzyme's ability to clear reactive oxygen species, thereby making tumor cells more susceptible to apoptosis." (PMID 40740240, 2025). "Additionally, GSTM3 is associated with the malignant tumour behaviours and poor prognosis in colon cancer and glioma." (PMID 38228715, 2024). "Interestingly, our data indicated that low GSTM3 expression is significantly associated with increased risk of tumor recurrence." (PMID 33482859, 2021). "To evaluate the clinical significance of GSTM3 in radiotherapy response and prognosis, we collected tumour tissues from 36 newly diagnosed NPC patients and 20 recurrent NPC patients." (PMID 38228715, 2024). "While the prognostic value of GSTM3 has been reported in various tumours, its potential as a prognostic indicator in NPC remains uncertain." (PMID 38228715, 2024). "To investigate the impact of GSTM3 on IR-induced ferroptosis in vivo, we subcutaneously injected 5-8F cells with stable GSTM3 overexpression into nude mice, leading to the formation of palpable tumours." (PMID 38228715, 2024). "We investigated the biological functions of glutathione S-transferase mu 3 (GSTM3) in cell lines and xenograft tumours." (PMID 38228715, 2024). "Low GSTM3 expression in ESCC tumorous specimens indicated aggressive tumor behaviors and predicted poorer disease-free survival." (PMID 33482859, 2021). "The staining index of GSTM3 in each informative tumor tissue that was greater than or equal to 6 was classified as high expression, whereas an index of 0–4 indicated low expression." (PMID 33482859, 2021). "Another multivariate analysis was conducted including the tumor location, histological differentiation, pathologic-T category, N status, and GSTM3 expression to evaluate the independent prognostic significance for disease-free survival in both cohorts." (PMID 33482859, 2021). "Our data demonstrated that GSTM3 expression is related to tumor differentiation; patients with low GSTM3 expression in tumor tissue exhibit an increased rate of poor differentiation in both mRNA cohort and protein cohorts." (PMID 33482859, 2021). "Further research on cell cycle analysis, apoptosis analysis, invasion assays and tumor formation in vivo are required to explore the tumor-suppressive ability of GSTM3 and its related pathway." (PMID 33482859, 2021). "After observation for 6 weeks, the results showed that GSTM3 knockdown promoted tumor growth compared to the shNC group." (PMID 32984010, 2020). "Our results proved that a high level of GSTM3 was correlated with a good prognosis which implies its anti-tumor effect in PC." (PMID 32984010, 2020). "We found GSTP1 and GSTM3 among the proteins that consistently increased their levels during tumor growth." (PMID 29774096, 2018). "We performed analyses on CC tumor proteome dynamics and identified GSTM3 and GSTP1 as novel potential therapeutic targets." (PMID 29774096, 2018). "GSTM3 plays a pivotal role of detoxification and clearance of reactive oxygen species (ROS) in tumour tissues." (PMID 29569387, 2018). "Probably, the low efficiency of protein reduction the treatment, particularly for GSTM3, is responsible for the low response in the tumor reduction." (PMID 29774096, 2018). "We studied the association between tumor pathology and the expression profile of seven phase I and II drug metabolizing genes (CYP1A1, CYP1B1, ALDH3A1, AOX1, GSTP1, GSTT1 and GSTM3) and some of their proteins." (PMID 26580399, 2015).
tumor (continued). "Glutathione S-transferase M3 (GSTM3) is a phase II transferase, however, recent studies have suggested that GSTM3 is a potential tumor suppressor." (PMID 25202346, 2014). "GSTM3, being an enzyme related to oxidative stress response, may contribute to tumor cell resistance to chemotherapy through the NF-κB signaling pathway." (PMID 40740240, 2025). "Notably, compared to the group treated with IR alone, GSTM3 overexpression combined with IR treatment resulted in a substantial reduction in tumour size and weight." (PMID 38228715, 2024). "By the same token, the question arises in terms of whether the polymorphism of the NRF2, GSTM3, SOD2 and GPX3 genes can affect the tumor progression, the prognosis of patients with testicular GCT and eventually the response to systemic chemotherapy." (PMID 35205816, 2022). "The findings of the present study provide evidence that GSTM3 may function as a tumor suppressor in ESCC and represents a potential novel prognostic biomarker for disease-free survival for resected ESCC patients." (PMID 33482859, 2021). "In conclusion, the results of the present study for the first time demonstrated that GSTM3 may function as a tumor suppressor in ESCC." (PMID 33482859, 2021). "The significance of GSTM3 expression levels in tumor prognosis remains inconsistent." (PMID 33482859, 2021). "The xenograft tumor model was applied to explore the effect of GSTM3 on cell proliferation in vivo." (PMID 32984010, 2020). "GSTM3 acted as a tumor suppressive factor and could potentially be an excellent candidate for target gene-based therapies for PC." (PMID 32984010, 2020). "GSTM3 overexpression could inhibit cell proliferation by enhancing G0/G1 retention which also indicated that GSTM3 exerted a tumor suppressing role." (PMID 32984010, 2020). "Moreover, silencing of GSTM3 induced ROS accumulation and promoted glycolysis in PC, indicating its tumor suppressive effect, and vice versa when GSTM3 was upregulated." (PMID 32984010, 2020). "Therefore, the present study aimed to investigate the role of GSTM3 as a tumor suppressor and a novel target of radioresistance." (PMID 25202346, 2014). "Notably, a decrease in GSTM3 abundance predicted tumour relapse and poor prognosis." (PMID 38228715, 2024). "It suggested that GSTM3 might act as a tumour suppressor via ROS activity regulation." (PMID 29569387, 2018). "Glutathione S-transferase M3 (GSTM3) has well-established roles in the detoxification and clearance of a variety of electrophilic compounds, including xenobiotics as well as substances generated by ROS damage to intracellular molecules, but also acts as a tumor suppressor." (PMID 26445099, 2015). "In GSTM3-inhibited T98G cells, upregulated genes SMARCA2 and SEPT9 were found to suppress tumor markers." (PMID 34209254, 2021). "Here we demonstrated that the inhibition of GSTM3 or GSTP1 activates JNK and p38 signaling leading cells to apoptosis and therefore decreasing the tumor volume." (PMID 29774096, 2018). "The treatment of these tumors with morpholinos against GSTM3 and GSTP1 resulted in a decrease of tumor volume by 10- and 6-fold, respectively." (PMID 29774096, 2018). "GSTM3 is not described to be involved in the recognition of tumor cells by immune cells, nor is there a known link to SPPL3." (PMID 39655358, 2025). "Remarkably, the newly diagnosed NPC samples exhibited strongly positive staining for GSTM3 and 4-HNE, while the recurrent tumour tissues showed relatively negative expression of GSTM3 and 4-HNE." (PMID 38228715, 2024). "Furthermore, in the subcutaneous tumour xenograft model, the expression of USP14 and FASN were increased, while the protein levels of GPX4 were decreased in the group with GSTM3 overexpression." (PMID 38228715, 2024).
tumor (continued). "Compared with the control groups, GSTM3 overexpression alone did not exhibit any impact on tumour growth in xenograft models, whereas IR effectively suppressed tumour growth." (PMID 38228715, 2024). "Indeed, this tumor expressed six of the NRF2 targets (CES1, CYP4F1, GSTM3, ARK1C1/3/4, AKR1C2, SRXN1, and PTGR1) more than 16-fold above their respective mean expressions for the entire cohort and 24 proteins more than 4-fold above their means." (PMID 37716475, 2023). "Finally, GSTM3 is regulated by lncRNA GAS5, a tumor suppressor that acts on tumor cells repressing proliferation, migration, and invasion, and promoting apoptosis and reactive oxygen species (ROS)." (PMID 37047296, 2023). "The relative expression level of GSTM3 was significantly downregulated in tumor tissues compared with paired adjacent nontumorous tissues (p = 0.001)." (PMID 33482859, 2021). "Furthermore, GSTM3 and GSTP1 knockdown showed that evasion of apoptosis was affected, and tumor proliferation was significantly reduced." (PMID 29774096, 2018). "However, the pattern was only confirmed for GSTM3 in HeLa tumors, while GSTP1 was not detectable in any tumor stage." (PMID 29774096, 2018).
infection (3 papers, 2018 to 2024). The state of being infected such as from the introduction of a foreign agent such as serum, vaccine, antigenic substance or organism. "Here we wondered if GSTM3 can interact with E7 from HPV18 in cells positive for infection with this HPV serotype." (PMID 29774096, 2018). "Compared to the uninfected control group, the number of host cells expressing GR and GSTM3 was significantly downregulated in the humanized mouse lungs as early as 2 weeks post infection, and this reduced level further persisted until 4 weeks post infection." (PMID 38338937, 2024). "Markers of oxidative stress triggered by the infection resulting in elevated ROS levels were matched by corresponding increases in the levels of antioxidant proteins, such as peroxiredoxin-1 (Prdx1), superoxide dismutase (Sod2), and glutathione S-transferase (Gstm3) in lung tissues." (PMID 36614003, 2022).
immune system diseases (1 paper, 2015). "Specifically, eight genes (IRF5, UBA7, TMTC1, GSTM3, FBN2, OAS1, PODXL, ITGA2) were previously associated with immune system diseases in at least one study." (PMID 25874939, 2015).
GSTM3 also shares sentences with these, for which no sentence is quoted: brain tumor (3 papers); cataract (3); colorectal cancer (2); esophageal cancer (2); glioblastoma (2); autism (1); brain cancer (1); brain disorder (1); Cirrhosis (1); cutaneous squamous cell carcinoma (1); diabetes (1); epilepsy (1); female infertility (1); gastric cancer (1); Hepatitis B (1); Hyperinsulinemia (1); idiopathic dilated cardiomyopathy (1); larynx cancer (1); legionellosis (1); liver cancer (1); liver fibrosis (1); lymph node metastasis (1); Meningeal tumors (1); metabolic dysfunction-associated steatotic liver disease (1); neurological disease (1); oral cancer (1); Oral leukoplakia (1); oropharyngeal cancer (1); osteosarcoma (1); pancreatic ductal adenocarcinoma (1).
A further 9 diseases each share a sentence with GSTM3 in 1 paper.